EZH2 (enhancer of zeste 2 polycomb repressive complex 2 subunit)
Diseases named in the same sentence as EZH2 in open-access papers (continued):
Sharing a sentence is not in itself a finding about the gene and the disease.
cancer (continued). "In recent studies, overexpression of EZH2 is related to poor prognostic in cancers of the prostate, breast, melanoma, endometrium, and pancreas." (PMID 24312307, 2013). "EZH2 has been historically considered an exclusively nuclear protein, although previous studies have described EZH2 immunoreactivity in the cytoplasm of cancer cells." (PMID 23448518, 2013). "The abnormal expression of EZH2 is involved in the tumorigenic processes and is regarded as a potential marker of aggressive types of cancer with poor prognoses." (PMID 24179546, 2013). "Recently, emerging evidence indicates that EZH2 silencing results in inhibitions of cell invasion and migration of several cancer cells and impairs the metastatic spreading in orthotopic xenograft models." (PMID 24345883, 2013). "As H3K27 tri-methylation is mainly catalyzed by EZH2 and associated with the PRC2-mediated epigenetic repression in cancer, we then monitored the changes of H3K27 expression after cells treated with DZNep." (PMID 24345883, 2013). "Identifying novel targets that are silenced by EZH2 will better reveal the molecular roles of EZH2 in cancer metastasis which will be beneficial to the development of chemotherapies targeting EZH2." (PMID 23826380, 2013). "Overexpression of EZH2 has been reported in prostate and breast cancers, and in several types of leukemia." (PMID 24202337, 2013). "Overexpression of EZH2 can lead to cancer progression mediated by deregulation of epigenetic mechanisms." (PMID 24313165, 2013). "Accumulated evidence has established that EZH2 plays pleiotropic tumorigenic roles in cancer progression by regulating a myriad of target genes in multiple cancers." (PMID 24345883, 2013). "Previous studies have indicated that the key cell cycle regulators including p16 and p21 were putative downstream effectors of EZH2 and can be induced in cancer cells." (PMID 24345883, 2013). "EZH2 is crucial in the chromatin control of genetic reprogramming of cancer stem cell self-renewal and differentiation that have been implicated in chemoresistance." (PMID 23940717, 2013). "Previous reports have indicate that DZNep potently depleted the core proteins of Polycomb complex including EZH2 and robustly triggered anti-cancer therapeutic effects in several cancer cells." (PMID 24345883, 2013). "Treating cancer cells with the EZH2 small molecular inhibitor, 3-Deazaneplanocin A (DZNep), restored DLC1 expression in different cancer cell lines, indicating that EZH2-mediated H3K27me3 epigenetic regulation of DLC1 was a common mechanism in human cancers." (PMID 23826380, 2013). "In cancer cells, high EZH2 expression was readily identified mainly in nucleus but rarely in cytoplasm." (PMID 24345883, 2013). "For example, decreased levels in certain microRNAs, such as miR101 and miR214, result in the overexpression of EZH2 in cancer, and thus factors governing mRNA stability and translation should also be measured." (PMID 23826629, 2013). "For the 59 UCB cases with high H3K27me3 expression, 61.0% of carcinoma cells on average stained positive for EZH2 protein." (PMID 24093096, 2013). "EZH2 transcriptionally silences cohorts of developmental regulators in stem/progenitors and cancer cells." (PMID 22662197, 2012). "As PRC2 proteins including EZH2 primarily epigenetically silence genes there has not been a comprehensive analysis of genes that are positively regulated by EZH2 in cancer." (PMID 23077658, 2012). "EZH2 expression and methylation status are known to be predictive of the progression and treatment outcomes of certain cancers." (PMID 22662197, 2012). "The mRNA levels of UTX, JMJD3 and EZH2 were significantly increased in cancer tissues compared to the adjacent tissues (P < 0.05), while the expression of p16INK4a mRNA was highly significantly upregulated in cancer tissues (P < 0.001)." (PMID 23057811, 2012).
cancer (continued). "Subsequently, the overexpression of EZH2 has been reported in several types of cancer including prostate, breast, bladder, gastric, lung, and HCC." (PMID 22962603, 2012). "Accumulated evidence shows that EZH2 contributes to various aspects of cancer by regulating a myriad of target genes." (PMID 22187039, 2012). "EZH2 (enhancer of zeste homolog 2) can be regarded as an oncogene and is frequently overexpressed in a wide variety of cancers, including RCC." (PMID 23057811, 2012). "Significantly, EZH2 has been implicated to play a key role in mediating both histone methylation and DNA methylation of HOXB13 gene in some cancer cells." (PMID 22808286, 2012). "Previous studies have revealed a number of possible mechanisms of EZH2 up-regulation in various cancers." (PMID 23251464, 2012). "The role of Ezh2 as a regulator of gene silencing and cell proliferation in cancer development has been extensively investigated; however, its function in heart development during embryonic cardiogenesis has not been well studied." (PMID 22312437, 2012). "Accumulated evidence indicates that EZH2 can be regulated in different types of human cancers at transcriptional, post-transcriptional and post-translational levels." (PMID 22187039, 2012). "The proliferation of cancer cells is mediated by increased expression of Enhancer of Zeste Homolog 2 (EZH2), a mammalian histone methyltransferase that contributes to the epigenetic silencing of target genes." (PMID 22662197, 2012). "Ezh2 is one of the most commonly misregulated genes in cancer, and recent work has shown that Pcl3 is misregulated in diverse cancers as well." (PMID 22438827, 2012). "These therapeutic approaches have indicated that EZH2 controls diverse phenotypic features of cancer including proliferation, invasiveness, metastasis and resistance to cell death." (PMID 23077658, 2012). "Expression of PcG proteins including BMI1 and EZH2 are often up-regulated in various cancers, particularly in their cancer stem cell fractions." (PMID 22606246, 2012). "The mechanism, which prevents EZH2 from binding to ADAMTS1 promoter in cancer cell-precocultured NAFs, is currently under investigation." (PMID 22514714, 2012). "Our Western blot analysis showed that EZH2 levels are significantly elevated in the cancer cell lines than in the benign human prostate epithelial cell line RWPE-1." (PMID 22272343, 2012). "The Enhancer of Zeste 2 (EZH2) protein has been reported to stimulate cell growth in some cancers and is therefore considered to represent an interesting new target for therapeutic intervention." (PMID 21765901, 2011). "It was recently shown that miR-101 can regulate EZH2 expression in cancer cells and affects cancer cell migration and invasion." (PMID 21297974, 2011). "Pioneering studies have shown that both SUV39H1 and EZH2 inhibitors exhibited cancer suppressive effects in vitro." (PMID 21347439, 2011). "We were particularly interested in miR-101 since this miRNA was recently shown to interact with EZH2 in different types of cancer, and predicted to bind the EZH2 3′-UTR at two sites." (PMID 21297974, 2011). "Consistently, in preclinical models of different cancers, the antitumor effect of EZH2 inhibition, obtained through the methyltransferase inhibitor 3'-deazanoplanocin (DZNep), is enhanced by addition of HDAC inhibitors." (PMID 21609503, 2011). "Conversely, EZH2 is abnormally overexpressed in a wide range of tumors as compared with corresponding normal tissues, its level of expression being correlated with cancer aggressiveness." (PMID 21609503, 2011). "Among these regulatory players, the histone methyltransferase enhancer of zeste homolog 2 (EZH2) is considered one of the most appealing epigenetic targets for therapy in human cancer." (PMID 21609503, 2011). "EZH2 and SUZ12, components of the polycomb PRC2 complex, have been implicated in several types of cancer." (PMID 21712824, 2011).
cancer (continued). "Deregulation of polycomb genes is pervasive in human cancer and over-expression of BMI-1 and EZH2 contribute to the tumorigenicity of established ESFT cells." (PMID 21559395, 2011). "Due to the growth-promoting role of EZH2 in various cancers, inhibition of EZH2 is currently discussed as an attractive novel strategy for cancer therapy." (PMID 21765901, 2011). "An additional component adding to the complexity of interpretation of H3K27me3 enrichment in particular is the newly discovered role of the H3K27me3 histone methyltransferase Ezh2 as a transcriptional activator on cell cycle- genes in cancer cells." (PMID 20161773, 2010). "Somatic mutations in both EZH2 and the H3K27 demethylase gene KDM6A (UTX) have been found in human cancer." (PMID 20565864, 2010). "It is therefore intriguing that p16INK4A, which is normally repressed in cycling cells by EZH2 via H3K27me3 and frequently undergoes DNA hypermethylation in cancer, is often overexpressed in HPV-positive carcinoma." (PMID 20724161, 2010). "The effect of EZH2 expression on cancer specific survival (CSS) was assessed by univariate and multivariate Cox regression analyses." (PMID 20920340, 2010). "The two chemical inhibitors, the S-adenosylhomocysteine hydrolase inhibitor 3-Deazaneplanocin (DZNep) and the histone deacetylase inhibitor LBH589, are reported to deplete EZH2 protein levels and reduce survival in cancer cells." (PMID 20634887, 2010). "One of the most important mechanisms is that many cancer-related genes are silenced by the enhancer of zeste homolog 2 (EZH2), which can specially trimethylate lysine 27 on histone H3 (H3K27) of the target gene promoters." (PMID 20028503, 2009). "A key component in the PRC2 complex is EZH2 histone methylase and similar to Bmi1, it is also elevated in various cancers." (PMID 19956605, 2009). "We have demonstrated that the PcG proteins BMI-1 and EZH2 represent promising target antigens for cancer immunotherapy." (PMID 17024127, 2006). "Further studies identified T-cell responses to both BMI-1 and another PcG protein, EZH2, in cancer patients and at relatively lower levels in some normal donors." (PMID 17024127, 2006). "Predicted CD8+ T-cell epitopes derived from BMI-1 and EZH2 also elicited T-cell responses as assessed by IFN-γ release confirming the presence of CD8 responses against these proteins in patients with cancer." (PMID 17024127, 2006). "The incidence of cancer cell invasion into the portal vein was significantly higher (P<0.001) in the high EZH2 expression group (26 of the 33, 79%) than in the low expression group (13 of the 33, 39%)." (PMID 15856046, 2005). "Further investigation is therefore needed to clarify the relationship between EZH2 and disease progression in cancer patients." (PMID 15856046, 2005). "Interestingly, chronic Cr (VI) exposure can induce cancer stem cell-like properties and cell transformation by significantly increasing EZH2 and MYC expression levels." (PMID 41362669, 2026). "Only a small proportion of cancer patients benefit from treatment with EZH2 inhibitors (EZH2is)." (PMID 42140904, 2026). "Furthermore, high EZH2 expression is also observed across various cancer types, offering additional therapeutic avenues." (PMID 40181550, 2026). "Active NRF1 and EZH2 expression may be a useful combined predictor for the treatment of cancers with EZH2is." (PMID 42140904, 2026). "It was shown to significantly downregulate EZH2 at both mRNA and protein levels in cancer." (PMID 41561226, 2026). "These RNA networks intersect with major oncogenic pathways, including PI3K/AKT/mTOR signaling, hypoxia responses, and epigenetic regulators such as EZH2, thereby affecting key cancer processes such as proliferation, epithelial-mesenchymal transition (EMT), and metabolic reprogramming." (PMID 42192969, 2026).
cancer (continued). "Together, our study decodes a previously hidden interrelationship between EZH2 and mRNA modification, which may be leveraged to advance the EZH2-targeting curative strategies in cancer." (PMID 41252201, 2026). "This leads to EZH2 ubiquitination and destruction in cancer of the breast cells." (PMID 41459628, 2026). "Remarkably, our above evidence supports a notion that EZH2 may further facilitate oncogenesis via enhancing the translation of a series of cancer regulators through its catalytic activity, with YTHDF1 playing a pivotal role in this process." (PMID 41252201, 2026). "Overall, the current work expands our knowledge regarding the convergence of a key histone modifier and a widespread RNA modification type, which may inspire a therapeutic advance in treating EZH2-dependent cancers." (PMID 41252201, 2026). "Additionally, we find that ANCR plays a significant role in the growth and metastasis of cancer of the breast, primarily by reducing the stability of EZH2." (PMID 41459628, 2026). "Both EZH2 and H3K27me3 levels were elevated in cancer tissues compared to normal tissues." (PMID 41544165, 2026). "The effect of NRF1 on the sensitivity of cancer cells to EZH2is is EZH2 dependent." (PMID 42140904, 2026). "To investigate whether and how epigenetic mechanisms contribute to these virus-induced effects, we examined the histone methyltransferase EZH2, a key regulator of chromatin repression frequently altered in cancer." (PMID 42043198, 2026). "Notably, inhibitors targeting the histone methyltransferase EZH2 have entered clinical trials, demonstrating the feasibility of modulating HKMTs for cancer therapy." (PMID 41203594, 2025). "Usp22 inhibits MCH-I expression through upregulating EZH2 in cancer cells." (PMID 41252204, 2025). "This increased heterogeneity might contribute to the oncogenic functions of mutant-EZH2, providing yet another explanation for the selective advantage it confers to the cancer cells." (PMID 40504770, 2025). "The overexpression of EZH2 in cancer cells may also be due to the regulation of some RNAs at different levels." (PMID 40028035, 2025). "The phosphorylation mediated by p38 at T367 promotes EZH2 cytoplasmic localization, which may regulate migration and invasion of cancer cells." (PMID 40028035, 2025). "Accumulating evidence indicates that EZH2 contains a hidden and partially disordered trans activation domain, which directly binds to transcription coactivator p300 and activates gene expression in cancer cells." (PMID 40028035, 2025). "Aiming at epigenetic modification of EZH2, the earliest EZH2 inhibitor was 3-Deazaneplanocin A. It was reported that 3-Deazaneplanocin A selectively inhibited the H3K27me3 and lysine 20 on histone H4, and reactivated silenced genes in cancer cells." (PMID 40028035, 2025). "Furthermore, TRIM25 promotes oxaliplatin resistance by stabilizing EZH2 through inhibition of its ubiquitination, enhancing EZH2-driven histone methylation and fostering cancer stemness." (PMID 41359051, 2025). "EZH2 and SUZ12 variants have been reported in other cancers and can be viewed through OncoKB." (PMID 40766612, 2025). "Notably, cancer-derived exosomes facilitate glycolysis, proliferation, and metastasis through the miR-198/EZH2 axis." (PMID 41226409, 2025). "Given the myriad of effects exerted by EZH2, targeting it may emerge as a powerful therapeutic agent for halting cancer progression and addressing existing challenges related to cancer treatment." (PMID 40028035, 2025). "Hence, the epigenetic regulation of gene expression by EZH2 is acknowledged as a key factor in modulating immune evasion, such as controlling the expression of PD-L1, in cancer cells." (PMID 40308579, 2025). "Also, it has been reported that in multiple types of cancer, targeting EZH2 can overcome anti-cancer drug resistance." (PMID 40028035, 2025).
cancer (continued). "A recent study has demonstrated that DCAF1 phosphorylates the T367 site of EZH2 to enhance its nuclear stability and enzymatic activity in colon cancer cells, resulting in elevated H3K27me3 levels and altered growth-regulating gene expression in cancer cells." (PMID 40164592, 2025). "Besides regulating the cell cycle directly, EZH2 can promote cancer development by participating in multiple signaling pathways." (PMID 40028035, 2025). "However, the frequent emergence of drug resistance has seriously affected their anti-cancer efficacy and EZH2 was demonstrated to take part in this process." (PMID 40028035, 2025). "In addition to AKT/EZH2/β-catenin axis, EZH2 also can promote the progression of cancer through the activation of the AKT/GSK3, PI3K/AKT/mTOR, and other pathways." (PMID 40164592, 2025). "MicroRNA-30d can inhibit the movement of cancer cells by targeting and inhibiting EZH2." (PMID 39944135, 2025). "In NEPC, EZH2 is essential for sustaining cancer cells’ aggressive and treatment-resistant nature." (PMID 41013839, 2025). "This has also further aroused people's attention to targeting EZH2 in cancer." (PMID 40028035, 2025). "Acknowledging that EZH2 possesses extensive cancer-promoting capabilities, a primary objective of future clinical and preclinical research lies in exploring the utilization of EZH2 inhibitors, aiming to maximize therapeutic outcomes by precisely targeting EZH2." (PMID 40028035, 2025). "Our data suggest that elevated circulating H3K27me3 levels might indicate overexpression of EZH2 in cancer cells, suggesting potential sensitivity to EZH2 inhibitors like tazemetostat." (PMID 40968252, 2025). "Notably, curcumin has been demonstrated to downregulate the expression of the PRC2 subunit EZH2 in various cancer cells." (PMID 40271060, 2025). "The involvement of EZH2 in PCB-induced carcinogenesis is supported by previous studies demonstrating that exposure to persistent environmental pollutants like PCBs can lead to epigenetic modifications, contributing to cancer risk." (PMID 40584614, 2025). "Importantly, both subpopulations were maintained in control and EZH2-inhibitor treated cells, suggesting this heterogeneity is an inherent feature of EZH2-mutant cancer cells." (PMID 40504770, 2025). "Targeting EZH2 represents a potential strategy to combine with existing immunotherapies for cancer." (PMID 41326356, 2025). "While the role of somatic PRC2 dysfunction in cancer is well established, the connection between germline mutations in PRC2 subunits and NDDs only began to emerge in 2012, with the discovery of de novo EZH2 variants as one of the first causes of an OGID syndrome." (PMID 41153408, 2025). "Among these, NAT1, BIRC3, EZH2, MAD2L1, ATP2A3, HMGA1, and BST2 are known cancer-associated genes." (PMID 41255601, 2025). "Indeed, EZH2 dependent suppression of the tumor suppressor genes during cancer progression promotes tumorigenesis." (PMID 40289112, 2025). "Additionally, EZH2 has been shown to directly influence DNA methylation, contributing to the silencing of tumor suppressor genes in cancer." (PMID 40004468, 2025). "It has been suggested that EZH2 inhibitors may prove effective in combatting cancer through the mechanism of synthetic lethality in tumors with ARID1A mutations." (PMID 39773749, 2025). "The Cysteine/methionine metabolism pathway, prominently featured by S-Adenosylmethionine and S-Adenosylhomocysteine metabolites, could be influenced by pan-cancer oncogenes EZH2 and SETDB1." (PMID 39982908, 2025). "Ezh2 plays a crucial role in cancer by promoting cell survival, proliferation, and invasion." (PMID 40182023, 2025). "However, research has revealed that EZH2 and KIF20A are strongly linked to the growth and prognosis of cancer and coexist in many prognostic indicators, offering crucial hints for further investigation." (PMID 40465746, 2025).